IL6 (interleukin 6)
Diseases named in the same sentence as IL6 in open-access papers (continued):
Sharing a sentence is not in itself a finding about the gene and the disease.
Q fever (11 papers, 2010 to 2025). A bacterial infection caused by Coxiella burnetii. "For example, in mycobacterial infections, IL6 expression can also alter or hinder IFNγ production, consequently resulting in Q-fever." (PMID 38391673, 2024). "The circulating TNF and IL-6 levels were markedly increased in patients with acute Q fever compared with controls." (PMID 20594295, 2010). "Physiologically, acute Q fever patients show increased serological levels of TNFα and IL-6, whereas patients with valvopathy progressed to chronic infection have even higher amounts circulating TNFα and type I IFN, as well as reduced IL-1 receptor antagonist (IL-1Ra)." (PMID 38459007, 2024). "In C. burnetii antigen-stimulated whole blood, a high proportion of monocytes from both controls (Group 1) and IGRA-positive donors with a clinical history of Q Fever (Group 5) produced TNFα (median 10.8% and 17.6%), IL-1β (median 55.8% and 66.6%) and IL-6 (median 43.3% and 55.5%)." (PMID 37885896, 2023). "This can be seen after Q fever, where elevated levels of IFN-gamma, IL-1 and IL-6 may underlie chronic fatigue." (PMID 34640355, 2021). "As was previously shown, PBMCs of QFS patients produce significantly more IL-6 than healthy controls, CFS patients, and asymptomatic Q fever seropositive controls, when stimulated with Q fever antigen." (PMID 31088495, 2019). "It identified five hub genes (IL4, IL6, IL1B, CD28, and AKT1) that may contribute to the progression of Q fever by regulating immune responses." (PMID 41468478, 2025). "Traditional markers for diagnosing and monitoring chronic Q fever are anti-phase I IgG titers, reflecting a specific B-cell derived humoral immune response and CRP, a product of an aspecific IL-6 mediated inflammatory response, used to detect complications and concomitant infections." (PMID 28793883, 2017). "In acute Q-fever IL-6 and CRP seemed predictive of more severe disease, but no support was found that these were associated with prolonged fatigue." (PMID 27223465, 2016). "During the Dutch Q fever outbreak (2007–2010), our group demonstrated that QFS patients exhibit signs of altered immunity through the monocyte-derived cytokines Tumor Necrosis Factor (TNF)α, interleukin (IL)-1β, and especially IL-6, together with the interferon (IFN)γ-axis." (PMID 33243243, 2020). "In our hands, previous stimulation experiments of PBMCs with LPS for 24 h did not result in a difference in IL-6, TNFα, or IL-1β production between CFS patients, QFS patients, asymptomatic Q fever seropositive controls, and healthy controls." (PMID 31088495, 2019).
rhinitis (11 papers, 2010 to 2025). An inflammation of the mucous membrane lining the nose, usually associated with nasal discharge. "Results of interest include: total effective rate; total nasal symptom score; rhinitis quality-of-life questionnaire; visual analog scale; laboratory test indicators: IgE, IL6, IL10, or TNF-α levels; recurrence rate; adverse events." (PMID 33761721, 2021). "After 3 months of work in burnt sugarcane harvesting the prevalence of rhinitis symptoms and IL-6 in nasal lavage increased." (PMID 29661675, 2019). "The outcomes of interest include: total effective rate; the total nasal symptom score; Rhinitis quality of life questionnaire (RQLQ); Visual Analog Scale (VAS); Laboratory inspection indicators: the level of IgE, IL6, IL10 or TNF-α; Recurrence rate; adverse events." (PMID 33546014, 2021).
scrub typhus (11 papers, 2012 to 2026). Scrub typhus is a rare dust mite-borne infectious disease caused by the Orientia tsutsugamushi bacterium and characterized clinically by an eruptive fever which is potentially serious. "It was reported that some cytokines, including IL-8, contribute to disease severity in patients with scrub typhus, and cytokines such as IL-6 and IL-10 were associated with the development of AKI." (PMID 28419138, 2017). "On day 4 post-infection, Karp induced significant elevation of transcriptional inflammatory signatures (Ccl2, Il33, Ifng) and inflammatory gene pathways (Il1, Il6, Tnf, Ifng), the characteristics of severe scrub typhus." (PMID 42112365, 2026). "Further investigation is warranted to reveal the unique roles of IL-6 and G-CSF and their potential as therapeutic strategies for severe scrub typhus." (PMID 38743761, 2024). "Plasma levels of IL-6, IL-8 and, particularly IL-10, were markedly higher in patients with scrub typhus than in those with murine typhus." (PMID 22192733, 2012). "Proinflammatory cytokines, such as TNF-α, IL-1β and interleukin-6 (IL-6), increase markedly in patients with scrub typhus, and attribute to the high fever occurring in most scrub typhus patients." (PMID 22723924, 2012). "Thus, although plasma levels of CRP, PTX-3 and IL-6 were markedly raised in scrub typhus patients, similar levels were found in infectious disease controls." (PMID 24516677, 2014). "Previous studies have shown increased plasma or serum levels of various cytokines in scrub typhus patients such as TNFα, IFNγ, IL-6 and IL-10, but these studies included a rather low number of patients (n = 9–55) and relatively few inflammatory mediators were examined." (PMID 24516677, 2014). "Murine cytokine expression data revealed that the two most virulent strains, Ikeda and Kato, induced higher levels of IL-6, IL-10, IFN-γ and MCP-1 than other strains, consistent with increased levels of these cytokines in patients with severe scrub typhus." (PMID 40587585, 2025). "In scrub typhus, PMN counts correlated (spearman’s Rho, p-value) with plasma levels of IL-6 (Rho = 0.257, p = 0.01), bleeding (Rho = 0.26, p = 0.041) seizure (Rho = 0.371, p = 0.002), confusion (Rho = 0.304, p = 0.015) and GCS (Rho = 0.22, p = 0.023), but not with ELA complex levels (p = 0.314)." (PMID 26317419, 2015).
seminoma (11 papers, 2022 to 2026). A radiosensitive malignant germ cell tumor found in the testis (especially undescended), and extragonadal sites (anterior mediastinum and pineal gland). "In metastatic tumour front tissue, transcripts relating to immune cell pathways, metabolism, inflammation and angiogenesis, and to the IL6 signalling pathway were higher when compared with non‐metastatic seminoma tumour fronts." (PMID 40693358, 2026). "Elevated IL6 levels are documented in seminomas, while dysregulated IL6 expression features in many cancers and is associated with tumour growth and invasiveness." (PMID 37048077, 2023). "While IL-6 was overexpressed in the seminomas of cSII/III patients compared to cSI patients, the opposite pattern was found in the serum of these patients." (PMID 35022523, 2022). "Among TGCTs, IL-6 has previously been described to be significantly (p < 0.001) upregulated in seminomas and in germ cell neoplasia in situ compared to normal testicular tissue or testicular tissue with hypospermatogenesis." (PMID 35022523, 2022). "Clinical trials targeting immune checkpoint molecules such as PD-1 for the treatment of TGCT mainly failed, probably due to our incomplete understanding of the TGCT immune microenvironment, but IL-6 has been considered as a potential immunotherapeutic target in seminoma." (PMID 38649788, 2024). "Interestingly, IL-6, encoding the pro-inflammatory cytokine IL-6, was not only found to be upregulated in TGCT, but its expression level was directly associated with the metastatic status of seminomas." (PMID 38649788, 2024). "Later, the authors used a co‐culture of TCam‐2 seminoma cells with peripheral blood mononuclear cells (PBMCs) and observed elevated IL6 expression in TCam‐2 cells after direct contact with PBMCs, pointing at the potential of the seminoma cell line to directly shape its surrounding microenvironment." (PMID 35811571, 2022). "We also identified key chemokines including IL6 and CXCL13, that hold promise for therapeutic strategies aimed at inducing TLS formation and amplifying antitumor immune responses in non-seminomas." (PMID 39528470, 2024). "Subsequently, a gene expression analysis via RT-qPCR was performed for the non-seminoma marker SOX2; the cytokine IL6, which is moderately produced also through tumor cells; and the proliferation and cell cycle genes KI67 and CDK4." (PMID 37174085, 2023). "Taken together, we unveiled the functionally discrete roles of IL-6 and TNFα in shaping the pro-inflammatory TME in seminomas, although we cannot exclude the possibility that tumor cells produce additional soluble factors like the chemokines CXCL10 that are involved in this process." (PMID 40649953, 2025). "In agreement with this hypothesis, an overexpression of IL-1β, IL-6 and TNF-α has been reported in seminoma." (PMID 37371875, 2023). "Moreover, a unique cytokine profile characterized by higher concentrations of interleukin 6 and other B-cell supporting or T-helper cell type 1 driven cytokines was described in germ-cell neoplasia in situ and seminoma samples, but not in normal spermatogenesis samples." (PMID 41343562, 2025). "In TGCTs, a varying expression profile of IL-6 was observed depending on its localization in the TME, and it was also found to differ between metastatic and non-metastatic seminomas." (PMID 40649953, 2025).
staphylococcus aureus infection (11 papers, 2011 to 2024). An infectious process in which the bacteria Staphylococcus aureus is present. "To further confirm the Nrf2-medited inhibition of IL6 gene induction in vivo, we utilized another inflammation model, that is, Staphylococcus aureus infection." (PMID 27211851, 2016). "Staphylococcus aureus infection induces severe inflammation, which leads to significant upregulation of TNF-α, IL-1β, and IL-6 in both lung tissues and cells." (PMID 38803378, 2024). "Staphylococcus aureus infection triggers early cytokine secretion, such as TNF-α, IL-1β, and IL-6, which promotes the inflammatory response and recruits other immune cells to combat invading microorganisms." (PMID 35935196, 2022).
vitamin B12 deficiency (11 papers, 2015 to 2025). A disease characterized by low serum levels of vitamin B12, either inherited or acquired. "Mice with vitamin B12 deficiency exhibited increased inflammatory marker levels such as IL-6, accompanied by leukocyte activation." (PMID 40625905, 2025). "Vitamin B12 deficiency increased plasma triglycerides, cholesterol and pro-inflammatory markers (such as tumor necrosis factor-alpha, interleukin-1 b and interleukin-6), as well as decreased adiponectin concentrations in mice." (PMID 39010125, 2024). "Neuropathological lesions in SACD have been found to be due to overproduction of the myelinolytic Tumor necrosis factor α (TNFα) and to the reduced synthesis of the two neurotrophic agents; the Epidermal growth factor (EGF) and interleukin-6 caused by vitamin B12 deficiency." (PMID 26385097, 2015). "Another thing is that the abnormal conditions affecting balance between IL-6 and TNF-α in the CNS may cause cobalamin deficiency, which leads to demyelination." (PMID 26435864, 2015). "Additionally, vitamin B12 deficiency can further lead to myelin damage by increasing levels of neurotoxic cytokines such as tumor necrosis factor-alpha (TNF-alpha) and decreasing neurotrophic cytokines such as interleukin-6 (IL-6)." (PMID 40083591, 2025). "In particular, cobalamin deficiency is related to the development of subacute combined degeneration, which is characterized by myelin degeneration and TNF-α-dependent CNS inflammation, accompanied by reduced concentrations of IL-6 and epidermal growth factor, which are considered neuroprotective." (PMID 31096592, 2019).
allergic contact dermatitis (10 papers, 2014 to 2026). An inflammatory skin condition caused by an immune response to direct contact between the skin and an allergen. "The proinflammatory cytokines IL‐1β, TNF‐α, and IL‐6 have been used as biomarkers to investigate periimplant diseases and are also produced in pathological allergic contact dermatitis." (PMID 40730516, 2025). "The initial response to ticks suggested by this study is similar to an allergic contact dermatitis that is elicited by keratinocytes and fibroblasts producing IL-6, CXCL-8 and CCL-2 to recruit inflammatory leukocytes." (PMID 28143523, 2017). "We found similar correlations for MCP-1 and IL-6; this demonstrates the decrease of their importance as markers of the activity of the inflammation in allergic contact dermatitis." (PMID 25183967, 2014). "In allergic contact dermatitis, CBD reduces IL-6, TNF-α and monocyte chemotactic protein-2 (MCP-2) in in poly-(I:C)–stimulated HaCaT cells, an in vitro model of this disorder." (PMID 38601151, 2024). "Furthermore, CBD can elicit anti-inflammatory effects in an allergic contact dermatitis model, where CBD treatment resulted in an elevation in the levels of AEA, and also blocked the increase of IL-6, CXCL8, TNF-α, MCP-2 in polyinosinic-polycytidylic acid-stimulated HaCaT keratinocytes." (PMID 37680639, 2023).
biliary tract cancer (10 papers, 2011 to 2024). "Similarly, in biliary tract cancers, high pretreatment levels of IL-6 and increasing levels during treatment were associated with short PFS and OS." (PMID 39502692, 2024). "For example, expression and secretion of IL-6 and TGFβ1 are interconnected in biliary tract cancer cells, strengthening invasion, EMT and chemoresistance." (PMID 38672477, 2024). "Interleukin-6 (IL-6) and TGFβ pathways also converge to potentiate malignancy and resistance to chemotherapy in biliary tract cancer." (PMID 31450767, 2019). "Treatment with TGF-β1 or IL-6 was reported to promote the activity of EMT and invasion in biliary tract cancer cell lines." (PMID 38519993, 2024).
Burkitt lymphoma (10 papers, 2009 to 2025). A rare form of malignant mature B-cell non-Hodgkin lymphoma. "Inhibition of the viral miRNA upregulates protein and mRNA levels of PTEN and IL‐6, has an important role in the pathogenesis of Burkitt lymphoma." (PMID 39185567, 2025). "Burkitt’s lymphoma children and adolescents in the study setting showed moderately higher levels of IL-6, IL-17A, IL-10 but low levels of IL-2, TNF-α and IFN-γ, possibly determined by prevailing infections." (PMID 29078819, 2017). "Previously, LMP1 has been shown to induce IL-6 and IL-8 secretion in epithelial cells via the NF-κB pathway and IL-10 in Burkitt lymphoma cells." (PMID 24886620, 2014). "Let-7 is downregulated in some cancers including Burkitt lymphoma thereby leading to elevated IL-6 production, likely due to activation of the oncogenic NF-κB-IL-6-Stat3 inflammatory pathway." (PMID 20204067, 2010). "Only the four Burkitt's lymphoma Raji, Daudi, BL-36 and Namalwa cells expressed IL-6; this latter expressed very low level IL-6, weakly detectable by PCR." (PMID 19956602, 2009). "A previous study has shown that IL-6 and TIMP-1 contribute to the chemoresistant niche promoting survival of tumor cells in a murine model of Burkitt’s lymphoma; however, the direct relationship between TIMP-1 and IL-6 remained unexplored." (PMID 31443242, 2019). "IL-6 KD in anti-CD19 CAR T cells against Burkitt’s Lymphoma resulted in no objective neurotoxicity, immunotoxicity, or tumorigenicity, while retaining the anti-tumor cytotoxicity and production of other cytokines." (PMID 41354926, 2025). "Here, we take advantage of MYC-, IL6- and IL6MYC-transgenic (Tg) mice that recapitulate important features of human Burkitt lymphoma (BL) or multiple myeloma (MM) to uncover up-regulated candidate cancer genes that might have been overlooked in other studies." (PMID 25838973, 2015).
cutaneous melanoma (10 papers, 2014 to 2026). A primary melanoma arising from atypical melanocytes in the skin. "In cutaneous melanoma, melphalan treatment was associated with enhanced expression of the pro-inflammatory cytokines: IL-1β, IL-8, and IL-6 and was found to induce apoptosis through ER stress and reactive oxygen species." (PMID 41160198, 2025). "Whole-genome sequencing also revealed that activating alterations in IL-6/JAK pathway genes occur frequently in aggressive cutaneous melanoma and correlate with accelerated progression." (PMID 42253503, 2026). "Current available data suggest that TNF-α and interleukins IL1B, IL-6, IL-8 and IL-18 can modulate the proliferation, survival and migration of cutaneous melanoma cells." (PMID 37047539, 2023). "Inflammation-supporting factors, predominantly IL-6 secreted by CAFs, enhance the aggressiveness of tumours, including cutaneous malignant melanoma." (PMID 34837514, 2022). "In humans, analyses of the TCGA dataset revealed positive mRNA correlations from cutaneous melanoma biopsies for expression of NLRP3 and IL‐6 (p=4.86e-20), IL‐6 and the STAT3 target gene Socs3 (p=1.82e-62), IL-1β and Socs3 (p=1.71e-31)." (PMID 34531850, 2021). "Strikingly, mRNA expression levels for IL-6, G-CSF, CXCL1, and other known tumor-promoting inflammatory factors showed strong positive correlation with those of PTGS2 in samples from human cutaneous melanoma." (PMID 26343581, 2015).
eating disorder (10 papers, 2020 to 2025). A broad group of psychological disorders with abnormal eating behaviors leading to physiological effects from overeating or insufficient food intake. "Studies have shown a relationship between IL-6 and eating disorders manifesting with emaciation and body composition abnormalities, including extremely low levels of body fat." (PMID 37762896, 2023). "In the full sample, associations between BMI and some inflammatory markers (e.g., GM-CSF, IL-8, IL-6, IL-16, IP-10) were mirrored by an inverse relationship with eating disorder psychopathology." (PMID 34442458, 2021). "We investigated the association between serum-levels of interleukin 6 (IL-6) and C-reactive protein (CRP) measured in childhood and eating disorders and related behaviours and cognitions in adolescence in a large general population sample." (PMID 32755646, 2020). "While some studies have found links between eating disorders and higher IL-6, no studies to our knowledge have prospectively examined associations of overeating behavior and IL-6." (PMID 36100924, 2022). "There was little evidence of an association between CRP and IL-6 and adolescent eating disorder outcomes." (PMID 32755646, 2020). "The aim of this study is to investigate whether serum levels of IL-6 and CRP at age nine years are associated with eating disorder diagnoses, disordered eating behaviours and cognitions during adolescence using a large UK general population prospective birth cohort." (PMID 32755646, 2020). "Our exposures were thirds of IL6 and CRP derived from serum measurements taken at age nine years, and outcomes were eating disorder diagnoses and self-reported disordered eating behaviours at ages 14, 16, and 18 years." (PMID 32755646, 2020). "The eating disorder is predicted to increase with six DRGs, which are LEP, IL6, GCG, SERPINE1, TNF, and INS." (PMID 32753925, 2020). "In another young transdiagnostic sample including male and female patients with AN and other eating disorders (mean age 17.7 years for female participants), patients showed normal serum TNF-α levels and lower concentrations of IL-6 and the pro-inflammatory cytokine IL-1 beta." (PMID 38461330, 2024). "One hypothesis posits that elevated levels of pro-inflammatory cytokines (IL-6 and TNF-α) in patients with IBD may contribute to the perpetuation of eating disorder symptoms." (PMID 39050133, 2024). "Additionally, the difference between discharge and admission of IL-6 showed a negative correlation with the difference in EDI-2 (rho = −0.471, p = 0.027), so an increase in IL-6 was associated with a decrease in self-reported symptoms of the eating disorder psychopathology." (PMID 36061277, 2022).